DAOA (D-amino acid oxidase activator)
Description:
May suppress DAO (D-amino acid oxidase) and SOD1 activity and promote their degradation. Has conversely also been suggested to function as a DAO activator. May stimulate the degradation of DDO (D-aspartate oxidase). May play a role in mitochondrial fission.
Synonyms: G72; LG72; SG72
Tractability: No criterion of Open Targets' tractability assessment is met for any kind of drug.
Gene: Protein-coding gene on chromosome 13 (105,465,867 to 105,491,034, forward strand). Ensembl gene ENSG00000182346.
Subcellular location: Cytoplasm, cytosol; Golgi apparatus; Mitochondrion
Gene Ontology:
Molecular function: protein binding
Biological process: D-amino acid metabolic process; negative regulation of amino acid biosynthetic process; positive regulation of protein catabolic process
Cellular component: Golgi apparatus; mitochondrion; perinuclear region of cytoplasm; cytosol
Genetic constraint (gnomAD): Loss-of-function variants: 14 observed, 15 expected, observed/expected ratio (o/e) 0.93, 90% interval 0.62 to 1.46. The upper end of that interval is the gene's LOEUF score, 1.46, which puts it in group 6 of 6, group 1 being the genes least tolerant of losing a copy. Missense variants: 211 observed, 167.04 expected, observed/expected ratio (o/e) 1.26, 90% interval 1.13 to 1.42. Synonymous variants: 68 observed, 55.98 expected, observed/expected ratio (o/e) 1.21, 90% interval 1 to 1.49.
Homologues: Orthologues: chimpanzee DAOA (47% identical).
Diseases named in the same sentence as DAOA in open-access papers:
DAOA is named in the same sentence as 16 diseases in open-access papers, as found by Europe PMC text mining. Sharing a sentence is not in itself a finding about the gene and the disease. The quoted sentences say what the papers report.
schizophrenia (45 papers, 2007 to 2025). A major psychotic disorder characterized by abnormalities in the perception or expression of reality. "The authors were able to identify G72 as a potential gene involved in schizophrenia pathophysiology and discovered that the gene encoded for a DAO binding protein, known as DAO activator (DAOA), capable of enhancing the enzyme-induced D-serine oxidation." (PMID 35883465, 2022). "Chromosome 13 is also responsible for type 2 breast cancer (BRCA2) and contains the DAOA locus associated with bipolar disorder and schizophrenia, among many other genetic diseases." (PMID 32244767, 2020). "The D-amino acid oxidase activator (DAOA, also known as G72) gene is a strong schizophrenia susceptibility gene." (PMID 30459659, 2018). "Previous studies have shown evidence for significant association of nucleotide variations at DAO and DAOA locus with schizophrenia and bipolar disorder." (PMID 29114206, 2017). "A study of 82 UHR individuals showed that 100% of the DAOA rs1341402 CC genotype carriers (n = 4) compared to 50% of the DAOA rs778294 AA genotype carriers (n = 10; A-allele protective against schizophrenia) progressed to psychosis within 24 months." (PMID 29326614, 2017). "Another study conducted in healthy male controls found that DAOA rs3916971 schizophrenia risk C-allele carriers had worse visual-spatial skills." (PMID 29326614, 2017). "Multiple genes encoded by chromosome 13 have been suggested to contribute to schizophrenia susceptibility, including DAOA, 5-HTR2A, KPNA3 and KPNB3, ESD, ATXN8OS, KFL5, EFNB2, and PCDH8." (PMID 22214315, 2012). "There are several studies suggesting that a locus located near the 3′ end of DAOA is associated with phenotypes characteristic of schizophrenia or the progression of the disease." (PMID 22454242, 2012). "Since it was not possible to narrow down the candidate region of chromosome 13, two genes were chosen for sequence analysis based on their robust association with schizophrenia: DAOA and 5-HTR2A." (PMID 22214315, 2012). "The gene DAOA, also known as G72, has also been shown to have a significant association with schizophrenia." (PMID 19445674, 2009). "DAO and DAOA are susceptibility genes for schizophrenia and bipolar disorders." (PMID 28428746, 2017). "We assessed the potential effect of DAO and DAOA SNPs on DAO and DAOA expression to understand whether such genetic variations known to be risk factors in schizophrenia play a role in the regulation of their expression." (PMID 28428746, 2017). "D-amino acid oxidase activator (DAOA), also known as G72, is directly implicated in the glutamateric hypothesis of schizophrenia." (PMID 23286827, 2013). "Besides, we have also performed the association studies in Taiwanese samples on NRG1 (8p12), DAO (12q24), and DAOA (12q33.2) as these three genes were reported to have strong association with schizophrenia in the literature." (PMID 23555897, 2013). "In addition, functional D-amino oxidase activator (DAOA) gene risk variant Arg30Lys (rs2391191) has also been implicated in cortical thinning in schizophrenia." (PMID 24386483, 2013). "However, we cannot find significant association of DAOA (G72) with schizophrenia." (PMID 23555897, 2013). "HMSE associated DAOA and visuospatial span associated DOCK9 have been linked to bipolar disorder and schizophrenia." (PMID 40665476, 2025). "The most down-regulated gene was d-amino acid oxidase activator (DAOA) (FC=0.062, FDR =0.009) involved in the glutamate receptor activation and it has been shown to be associated with schizophrenia." (PMID 36226068, 2022). "For instance, pLG72, also known as d-amino acid oxidase activator (DAOA) and able to modulate d-amino acid metabolism, is thought to be highly related to AD and schizophrenia pathogenesis." (PMID 34681579, 2021). "Pilot studies have used machine learning models with NMDAR-mediated biomarker like d-amino acid oxidase activator (DAOA, also known as G72) protein level to detect schizophrenia." (PMID 33803217, 2021).
schizophrenia (continued). "The D-amino acid oxidase (DAO) protein and its interaction partner, the D-amino acid oxidase activator (DAOA, also known as G72) protein, have been implicated as two key proteins in the N-methyl-D-aspartate receptor (NMDAR) pathway for schizophrenia." (PMID 32582679, 2020). "The present study aimed to extensively evaluate the contribution of DAOA and COMT genes in susceptibility to schizophrenia and bipolar I disorder." (PMID 30719257, 2018). "We also do not have schizophrenia brain samples to comment on regulation and expression of DAO and DAOA mRNA and protein across different brain regions in schizophrenia." (PMID 28428746, 2017). "DAOA and NRG1 polymorphisms were shown to predict the transition to schizophrenia in individuals at HR/UHR for psychosis." (PMID 29326614, 2017). "Studies have demonstrated an association between schizophrenia and d-amino acid oxidase (DAO), DAO activator (DAOA)/G72, and neuregulin 1 (NRG1) single-nucleotide polymorphisms (SNPs)." (PMID 29326614, 2017). "Considerable effort has been put forth to identify genes associated with schizophrenia, and multiple predisposing genes have been identified, including CHRNA7, DAOA, COMT, DTNBP1, NRG1, DISC1, GRM3, and PRODH." (PMID 22214315, 2012). "In the case of schizophrenia, a population-based analysis has revealed four genes, DAAO (DAO), DAOA, DTNBP1 and NRG1, to be associated with the schizophrenia." (PMID 19379523, 2009). "Moreover, single nucleotide polymorphisms in the DAOA gene, which encodes for the DAO activator protein G72, have been associated with schizophrenia and autism spectrum disorder." (PMID 38982054, 2024). "DAO and DAOA genes are alleged to be involved in pathophysiology of neuropsychiatric disorders such as schizophrenia and bipolar disorder, but the interactions between these genes remains unclear to date." (PMID 29114206, 2017). "The primary analyses did not demonstrate associations between schizophrenia and any of the 32 studied DAOA, DAO, PPP3CC, and DTNBP1 SNPs." (PMID 23497497, 2013). "Furthermore, abnormal proteins encoded by schizophrenia susceptibility genes (PRODH, DISC1, DAOA, NRG1, G72) cause oxidative stress and/or hypersensitivity to oxidative stress or mitochondrial dysfunction." (PMID 24027504, 2013). "NRGN, like DAOA, is involved in glutamate pathway regulation and may mediate effect of hypoglutamatergic function with impact on neural substrates in schizophrenia." (PMID 24386483, 2013). "The biological functions of DAO and DAOA are involved in the hypothesized hypofunction of NMDA receptor complex as the potential pathogenesis of schizophrenia." (PMID 23555897, 2013). "Interestingly, expression of G72 (DAOA) in schizophrenia has also shown a cohort effect with a larger change in schizophrenia in one series than the other." (PMID 17880399, 2007). "In addition to this genome-wide association studies provided no further evidence for an association of DAOA with schizophrenia or mood disorders challenging the previous positive findings." (PMID 20667145, 2010). "DAOA and COMT genes are two potential candidates for involvement in schizophrenia and bipolar disorder molecular mechanisms." (PMID 30719257, 2018). "The results showed that three of these positions were associated with both diseases and one position was associated with bipolar I. Thus, there are possibilities for DAOA and COMT genes variations to be involved in schizophrenia and bipolar I disorders." (PMID 30719257, 2018). "We aimed to estimate the role of two talent genes: DAOA in neurotransmission of glutamate and COMT in neurotransmission of dopamine to guide the treatment of schizophrenia and bipolar disorder." (PMID 30719257, 2018). "In conclusion, this result supports the hypothesis that variations in DAOA and COMT genes may play a role in schizophrenia and bipolar disorder." (PMID 30719257, 2018).
schizophrenia (continued). "Although the effects of these DAO and DAOA nucleotide variations on their mRNA and protein expression in schizophrenia is not yet studied, these genes still remain as candidate genes for schizophrenia because of their role in the glutamatergic signaling." (PMID 29114206, 2017). "Three of these loci (MTHFR, DAOA, ARVCF) had never been implicated by a schizophrenia GWA study." (PMID 31455759, 2019). "Five of these top eight LD-independent loci (MTHFR, PDE4B, DAOA, ARVCF, TRAM1L1/NDST3) were not located within risk loci identified in the largest schizophrenia GWA study produced by the PGC and three loci (MTHFR, DAOA, ARVCF) had never been implicated by a schizophrenia GWA study." (PMID 31455759, 2019). "However, a recent genome-wide association study conducted by the Psychiatric Genomics Consortium found that out of 108 schizophrenia-associated loci, none were within DAO and DAOA gene regions (Schizophrenia Working Group of the Psychiatric Genomics Consortium, 2014)." (PMID 28428746, 2017). "Three (MTHFR, DAOA, ARVCF) of these loci had not been reported in a schizophrenia GWA study within the Asian or Caucasian populations." (PMID 31455759, 2019). "Thus, there is an urgent need for new drugs for the treatment of negative symptoms and cognitive deficits of schizophrenia, which might be achieved by understanding the interaction between DAO and DAOA, and their subsequent effect on NMDA receptors." (PMID 29114206, 2017).
bipolar disorder (11 papers, 2009 to 2025). A disorder of the brain that causes unusual shifts in mood, energy, activity levels and the ability to carry out day-to-day tasks. "Furthermore, DAOA has been associated with other psychiatric disorders and phenotypes such as major depression, bipolar disorder and bipolar disorder severity." (PMID 22454242, 2012). "In several independent studies, D-amino acid oxidase activator (DAOA) and Catechol-O-methyltransferase (COMT) have been found to be associated with bipolar disorder." (PMID 23861766, 2013). "Our finding that cognitive manic symptoms in patients with bipolar disorder was associated with genetic variants in the DAOA and COMT genes, in both case-case and case-control analyses, supports that impaired cognitive functioning in general might be associated with the DAOA and COMT genes." (PMID 23861766, 2013). "The DAOA gene acts through the N-methyl-D-aspartate (NMDA) receptors that have a central role in memory function and synaptic plasticity and have been shown to be modified in bipolar disorder." (PMID 23861766, 2013).
psychosis (5 papers, 2013 to 2018). "Although no direct link has been revealed between genetic polymorphism in these genes and NMDA receptor function, the present results support previous reports implicating the DAOA as susceptible genes for psychotic disorders." (PMID 30719257, 2018). "We were unable to detect DAO and DAOA mRNA using qRT-PCR in the whole blood of individuals at-risk for psychosis, which is in line with a study that used RNA sequencing to detect DAO and DAOA mRNA in healthy participants." (PMID 29326614, 2017). "Previous studies have linked polymorphisms in the DAOA gene with the occurrence of neuropsychiatric symptoms such as depression, apathy, aggression, delusions, hallucinations, and psychosis in AD." (PMID 26949549, 2016). "Polymorphisms in DAOA have been associated with the occurrence of neuropsychiatric symptoms such as depression, apathy, aggression, delusions, hallucinations, and psychosis in AD." (PMID 26949549, 2016). "The evidence for DAOAs involvement in psychosis has been growing with several genetic studies finding an association between polymorphisms in the G72 gene which encodes DAOA, and the development of psychosis as well as severity of positive symptoms." (PMID 23805071, 2013). "The nominal associations between DAOA rs746187 and the RDoC-negative valence system: loss, and that between DAOA rs3916971 and the RDoC cognitive system: visual perception, points to the possible role of DAOA variations in modulating endophenotypes underlying psychosis risk." (PMID 29326614, 2017). "A recent study found a nominal association of DAOA rs3916971 with a psychotic disorder." (PMID 29326614, 2017). "DAOA gene (13q34) and COMT gene (22q11) are not only associated with psychotic disorders, but also play a key role in glutamatergic and dopaminergic neurotransmissions (Ross, Margolis, Reading, Pletnikov, & Coyle, 2006)." (PMID 30719257, 2018). "In a 3-year prospective study cohort of 185 individuals (age: 13–35 years) at high risk and ultra-high risk (UHR) for psychosis, we assessed DAO (rs3918347, rs4623951), DAOA (rs778293, rs3916971, rs746187), and NRG1 (rs10503929) SNPs and their mRNA expression." (PMID 29326614, 2017). "We examined associations of DAO, DAOA, and NRG1 SNPs with risk profiles in individuals at risk for psychosis." (PMID 29326614, 2017). "Our data provided further evidence that the DAOA locus or COMT locus may contribute in the pathophysiology of psychotic disorders." (PMID 30719257, 2018). "Our data provided further evidence that the DAOA locus or COMT locus may play roles in the pathophysiology of psychotic disorders." (PMID 30719257, 2018). "Thus, there is ambiguity regarding the association of DAOA and NRG1 polymorphisms with the transition to psychosis." (PMID 29326614, 2017). "While the data from the study may seem damning to aspirations of DAOA as a susceptibility gene for psychosis, the authors for this study did not differentiate between brain regions other than the amygdala and the caudate nucleus." (PMID 23805071, 2013).
mood disorder (2 papers, 2010 to 2019). A cognitive disorder a disturbance in which the person's mood is hypothesized to be the main underlying feature. "Genetic association studies of the DAOA gene with major mood disorders have primarily focused on the following seven single-nucleotide polymorphisms (SNPs): rs2391191, rs3918342, rs1421292, rs3916965, rs778294, rs947267, and rs1935062." (PMID 31637017, 2019). "Taken together, our data support a cis-regulatory effect on DAOA expression by which disease-associated SNPs underpin the pathogenesis of major mood disorders." (PMID 31637017, 2019). "Our findings confirmed that DAOA is a risk gene for major mood disorders and might provide a better understanding of the potential biological mechanism underlying major mood disorders." (PMID 31637017, 2019). "However, further studies are necessary to investigate whether the expression levels of DAOA are changed in subjects with major mood disorders compared with the levels in healthy subjects." (PMID 31637017, 2019).
psychiatric disorder (8 papers, 2009 to 2022). A disorder characterized by behavioral and/or psychological abnormalities, often accompanied by physical symptoms. "Our finding are consistent with other studies showing genetic associations between the COMT and DAOA genes and impaired cognition both in psychiatric disorders and in the general population." (PMID 23861766, 2013). "Subsequently, numerous genetic association studies made the DAOA/G30 gene complex one of the most intriguing susceptibility loci for the major psychiatric disorders." (PMID 20667145, 2010). "In the last years, several susceptibility genes for psychiatric disorders have been identified, among others G72 (also named D-amino acid oxidase activator, DAOA)." (PMID 19778423, 2009). "The main protein product of this locus is the longest G72 splice variant (LG72) protein (G72 protein, also termed D-amino acid oxidase activator (DAOA)), whose function in relation to psychiatric disorders remains obscure." (PMID 35207732, 2022). "The COMT and DAOA genes may contribute to the pathophysiology of psychiatric disorders, and especially cognitive manic symptoms, by the combined effect of dopaminergic and glutamatergic pathways." (PMID 23861766, 2013). "The DAOA/G30 (D-amino acid oxidase activator) gene complex at chromosomal region 13q32-33 is one of the most intriguing susceptibility loci for the major psychiatric disorders, although there is no consensus about the specific risk alleles or haplotypes across studies." (PMID 20667145, 2010).
DAOA also shares sentences with these, for which no sentence is quoted: Alzheimer disease (3 papers); depression (3); Cognitive Deficits (2); atherosclerosis (1); autism spectrum disorder (1); bipolar I disorder (1); cancer (1); genetic diseases (1); hepatocellular carcinoma (1); mental disorder (1); panic disorder (1).